SLC7A11 (solute carrier family 7 member 11)
Diseases named in the same sentence as SLC7A11 in open-access papers (continued):
Sharing a sentence is not in itself a finding about the gene and the disease.
tumor (continued). "CD8+ T cells induced ferroptosis in tumor cells through IFN-y-dependent SLC7A11 downregulation." (PMID 34938318, 2021). "We speculate that the miR-375/SLC7A11 axis might be a common phenomenon in tumor progression, which should be explored in the future." (PMID 34090492, 2021). "By inhibiting cell ferroptosis, the overexpression of SLC7A11 promotes tumor growth." (PMID 34123855, 2021). "Moreover, murine MC38 colon cancer and Pan02 pancreatic cancer cells, harbouring a CRISPR-Cas9-mediated Slc7a11 knockout displayed impaired in vivo tumour growth accompanied by increased ROS levels and decreased GSH levels." (PMID 31936571, 2020). "Notably, ectopic expression of SLC7A11 inhibits ferroptosis and abolishes the tumor suppressive function of p533KR in xenograft tumor models." (PMID 33182266, 2020). "When investigated, ferroptosis in CD8 + T cells that is activated by cancer immunotherapy, the interferon-gamma (IFNγ), downregulates the expression of SLC3A2 and SLC7A11, impairs the uptake of cystine by tumor cells, and as a consequence, promotes tumor cell lipid peroxidation and ferroptosis." (PMID 32372896, 2020). "Moreover, by analyzing gene expression in GSE6764 cohort, we found that the expression levels of PDSS1, CDCA8 and SLC7A11 were significantly higher in tumor tissue than those in liver nodules." (PMID 32887635, 2020). "Another limitation in our understanding of xCT necessity in cancers is a lack of a conditional mouse SLC7A11 knockout allele to study tumor specific deletion of xCT in vivo." (PMID 31100816, 2019). "Overexpression of these microRNAs compromises cell viability, proliferation, and invasion of various cancer cells, likely through SLC7A11 repression, and they are downregulated in various human cancers, suggesting tumor suppressive functions of these microRNAs." (PMID 29764521, 2018). "We demonstrate that SLC7A11-targeted inactivation, pretreatment with the xCT inhibitory compound erastin, and culture in cystine-free media provide potent radiation sensitization of xCT+ tumor cells, in vitro and in xenograft." (PMID 30190786, 2018). "Therefore, we assumed that miR‐375 functions as a tumor‐suppressing role in OSCC via downregulating SLC7A11 expression." (PMID 28627030, 2017). "Importantly, we show that endogenous expression of SLC7A11, a key component of system xC−, reliably predicts tumour response to these therapies." (PMID 28348409, 2017). "Moreover, we demonstrate that SLC7A11 expression is a reliable predictive biomarker for tumour response to these therapies." (PMID 28348409, 2017). "Collective data suggested that miR‐375 served as a tumor suppressor via regulating SLC7A11." (PMID 28627030, 2017). "Moreover, SLC7A11 has emerged as a central hub linking ferroptosis and tumor suppression functions." (PMID 40136455, 2025). "Consequently, targeting SLC7A11 has been shown to impede oncogenic KRAS‐driven tumour growth." (PMID 39354653, 2025). "Indeed, tumor cells may significantly enhance their oxidative stress defense ability by upregulating the SLC7A11/GSH/GPX4 axis, achieving drug resistance and survival to ferroptosis." (PMID 40229247, 2025).
tumor (continued). "Consequently, upregulation of SLC7A11 significantly enhances tumor cell resistance to ferroptosis." (PMID 40458724, 2025). "Additionally, exploration of the combined use of SLC7A11 inhibitors with existing chemotherapy agents, targeted therapy drugs, and immune checkpoint inhibitors may offer enhanced anti-tumor efficacy." (PMID 39569390, 2025). "As the most critical regulator of ferroptosis in HCC, SLC7A11 centrally regulates adaptive glutathione metabolism by conferring specificity for cystine uptake, which was found to be highly overexpressed in HCC cells and tissues and displayed a significant association with tumor progression." (PMID 40390765, 2025). "Besides, the IFN-γ released from CD8+ T cells could downregulate the SLC7A11 expression and glutamate-cystine antiporter system xc- subunits, which impairs the tumor cells’ cystine uptake and promotes cancer cell ferroptosis and lipid peroxidation." (PMID 41285711, 2025). "However, excessive SLC7A11 activation may trigger disulfidptosis, thereby limiting tumor development." (PMID 40520902, 2025). "Notably, disulfidptosis predominantly affects tumor cells exhibiting elevated levels of SLC7A11." (PMID 41185600, 2025). "Similar to other oncogenes, HIF-1α increases HIF-1α stimulates SLC7A11 expression, facilitating the exchange of glutamine with cystine, elevating glutathione levels within tumor cells, preventing the accumulation of ROS within tumor cells and impeding the occurrence of ferroptosis in tumor cells." (PMID 38172980, 2024). "Besides, the Western blot results were consistent with the prediction data, which meant that in the MAD2L2 over-expressed OVCA cells, mTOR might upregulate SLC7A11 to restrain ferroptosis and promote tumor growth in OVCA cells." (PMID 38167649, 2024). "Moreover, inhibitors of the PRMT1/SLC7A11 axis could delay tumor progression in CRC with low LPCAT2 expression, making it a potentially effective treatment for CRC." (PMID 38605214, 2024). "In addition, this study found that glucose transporter 1 inhibitors can effectively inhibit cell glucose uptake, thereby inducing disulfide death in SLC7A11 overexpressing cells; the inhibitor also has a significant effect on tumor growth with high expression of SLC7A11 in mice." (PMID 38167017, 2024). "Thus, GLUT suppression-induced disulfidptosis may be an effective treatment strategy for SLC7A11 high-expression tumor cells." (PMID 38649690, 2024). "In addition, the CNVs of SLC7A11, and SLC3A2 were negatively linked with their expression in most tumor types, while the CNVs other disulfidptosis genes were positively linked with their expression, uncovering that the CNVs contributed to abnormal expression of the disulfidptosis genes." (PMID 39605832, 2024). "Therefore, our research suggests that KCNA1 may promote tumor growth and invasion by upregulating the expression of SLC7A11 and inhibiting ferroptosis, making it a promising therapeutic target for GBM." (PMID 38172959, 2024). "They found that tumor cells having high level of SLC7A11 expression were more sensitive to the level of glucose and glutamine restrictions than these cells with low level of SLC7A11 expression, which may due to the high nutrient dependence of tumor cells." (PMID 38774759, 2024). "Notably, tumor volume of WT and Slc7a11-KD tumors remained comparable upon CD8+ T-cell depletion." (PMID 38360744, 2024). "Additionally, SLC7A11 is also involved in promoting tumor metastasis and immune evasion." (PMID 39125853, 2024).
tumor (continued). "IFNγ released by CD8(+)T cells inhibits the expression of SLC7A11 synergistically, leading to the activation of ferroptosis, thereby enhancing anti-PD-L1 anti-tumor immunotherapy, enhancing lipid oxidation and ferroptosis in tumors, and improving tumor control." (PMID 39192972, 2024). "Interestingly, a consistent reduction in SLC7A11 methylation was observed in tumor tissues." (PMID 38420162, 2024). "It is worth noting that there are indications that the overexpression of SLC7A11 in cancerous tumors can increase the activity of the PD-L1 pathway, resulting in the infiltration of tumor-associated macrophages (TAM) and myeloid-derived suppressor cells (MDSC) within the tumor." (PMID 39807126, 2024). "However, other researchers observed that inhibition of SLC7A11 expression may contribute to the growth and proliferation of tumor cells." (PMID 38774759, 2024). "Therefore, targeting molecules such as GPX4 and SLC7A11 to induce ferroptosis may provide a promising strategy to overcome tumor resistance and offer a new avenue for cancer treatment." (PMID 39771583, 2024). "Besides, SLC7A11 expression in the tumor was also significantly decreased." (PMID 38189879, 2024). "In conclusion, TNBC is an aggressive and heterogeneous tumor that requires more selective treatment, and the xCT/NRF2/OSGIN1 axis is a novel specific target for the treatment of MSL/CL subtypes overexpressing SLC7A11, which may be more effective than GSH depletion." (PMID 38600165, 2024). "Also, inhibition of SLC7A11 with sulfasalazine reduced tumor cell proliferation and invasion." (PMID 38705513, 2024). "SLC7A11 may regulate tumour immunity and could be a potential therapeutic target for LUAD." (PMID 37880315, 2023). "Thus, it promotes SLC7A11 transcription, influencing tumor cell ferroptosis." (PMID 37056388, 2023). "However, the role of SLC7A11 in anti-tumor immune cells needs further investigated." (PMID 37277776, 2023). "This suggests that SLC7A11 may contribute to distant tumour migration." (PMID 37919768, 2023). "In addition, the tumor suppressor BAP1 decreases H2Aub occupancy on the SLC7A11 promoter and represses SLC7A11 expression in a deubiquitinating-dependent manner, that is, BAP1 inhibits cystine uptake by repressing SLC7A11 expression, leading to elevated lipid peroxidation and ferroptosis rates." (PMID 37580393, 2023). "Notably, ferroptosis-associated miR-5096 can not only target SLC7A11 to increase ROS and iron accumulation directly, but also regulate EMT marker expression and inhibits the metastatic potential of the cells, thus hindering tumor metastasis." (PMID 37369681, 2023). "Regulating the expression of SLC7A11 may be a potential target for tumor immunotherapy." (PMID 37880315, 2023). "However, several studies have suggested that the overexpression of SLC7A11 can promote tumor progression by inhibiting ferroptosis, contrary to Liu’s hypothesis." (PMID 38116315, 2023). "Therefore, the inhibition of SLC7A11 can enhance the anti-tumor effect of immune cells." (PMID 38137387, 2023). "In summary, SLC3A2 and SLC7A11, which play an important role in glutathione synthesis, play a role in resisting oxidative stress, protecting cells from iron-mediated death, and promoting the survival and metastasis of tumour cells through their respective effects." (PMID 37829798, 2023). "Targeted inhibition of SLC7A11 may enhance the tumour immune response." (PMID 37880315, 2023). "Similarly, SLC7A11 abrogated the suppressive effect of YY2 overexpression on tumor growth rate." (PMID 35246964, 2022). "Therefore, more in-depth insights into the regulatory mechanisms of SLC7A11 in tumor metabolism could provide us with important clues for cancer treatment." (PMID 35884471, 2022).
tumor (continued). "Indeed, a chemical drug called erastin targeting SLC7A11 is identified and exhibits great lethality in human tumor cells through an oxidative cell death known as ferroptosis, which rapidly becomes a hot topic in the research field of regulated cell death (RCD)." (PMID 35178349, 2022). "Finally, in mouse xenograft models, knocking down Uc.339 in LLC cells was able to inhibits tumor growth by blocking the axis of Uc.339/miR-339/SLC7A11 in vivo, but miR-339 inhibitors could reverse this inhibition." (PMID 35399708, 2022). "Furthermore, immunotherapy sensitizes tumors to radiotherapy by promoting tumor-cell ferroptosis through IFNγ-induced SLC7A11 suppression, suggesting that ferroptosis may serve as a determinant of synergy between radiotherapy and immunotherapy." (PMID 35847022, 2022). "Thus, induction of ferroptosis in tumor cells through inhibition of SLC7A11 may be a promising treatment for use in patients." (PMID 35898880, 2022). "Finally, we selected the SLC7A11 inhibitor sulfasalazine to ascertain whether sulfasalazine can foster methionine dependence of tumor cells." (PMID 35123415, 2022). "In addition, low SLC7A11 expression may also be a metabolic vulnerability of cells, and further inhibition of SLC7A11 may also inhibit tumour growth or survival." (PMID 35804831, 2022). "And NCOA4-related ferritinophagy was triggered by NDV, which could increase the level of intracellular ROS and ferrous iron, and then trigger ferroptosis, indicating that NDV could kill tumor cells in a ferroptotic way by inducing ferritinophagy or inhibiting SLC7A11." (PMID 36160441, 2022). "Another study exploring the correlation between radiotherapy and ferroptosis also revealed that tumor antigen-specific CD8 T cells or IFN-γ could induce ferroptosis in melanoma cells via suppression of SLC7A11, and this effect was enhanced when radiotherapy was combined with IFN-γ." (PMID 35399527, 2022). "Therefore, the researchers found that tumour growth could be suppressed by inhibiting SLC7A11 to increase ferroptosis." (PMID 35804831, 2022). "Our results indicate that the anti‐tumour effect induced by METTL14 might be intervened by SLC7A11." (PMID 34609072, 2021). "SLC7A11 is upregulated in several human tumor tissues and may function as an oncogene." (PMID 34611144, 2021). "Moreover, we speculate that blockade of SLC7A11 activity might even enhance T cell function in the tumour, as T cells are partially dependent on extracellular cysteine, taken up via SLC1A5, to satisfy their demand." (PMID 34541580, 2021). "Interestingly, the components in tumor microenvironment could also promote or restrain tumor ferroptotic cell death by influencing the SLC7A11 expression level." (PMID 34938318, 2021). "Notably, although all BGC-823 cell lines could form tumors, cells with miR-375 overexpression as well as SLC7A11 overexpression showed an increase of tumor size and weight compared with that in cells with miR-375 overexpression alone." (PMID 34090492, 2021). "Finally, CISD1, ATP5MC3, PGD, SLC7A11, ACSL3, and FANCD2 expression was confirmed to significantly correlate with tumor mutational burden (TMB), microsatellite instability (MSI), immune cell infiltration, cellular checkpoint dysfunction, and cancer sensitivity to drugs." (PMID 35320929, 2021). "It has been reported that SLC3A2 deletion results in a downregulation of SLC7A11 levels, indicating that SLC3A2 is required to maintain SLC7A11 stability and its deficiency will impair the integrity of the system Xc−, thus sensitizing tumor cells to ferroptosis." (PMID 33425217, 2020).
tumor (continued). "In addition, SLC7A11 (cystine transporter, xCT), a cisplatin resistance associated gene, was found to be overexpressed in 4 out of 5 (80%) cases of CDC tumors tested, as compared to matched non-tumor tissue." (PMID 27144525, 2016). "Significantly, Erastin-a SLC7A11 inhibitor-overcame YBX1-mediated resistance, synergizing with 5-Fu to induce ferroptosis and suppress tumor growth." (PMID 41980917, 2026). "IFN‐β can reduce the expression of SLC7A11 and SLC3A2 on the tumor cell membrane, disrupt the tumor cell's antioxidant system, and induce tumor cell ferroptosis." (PMID 41560416, 2026). "Combined CsA and chemotherapy treatment significantly enhances tumor regression, as evidenced by increased 4‐HNE and reduced SLC7A11 expression in vivo." (PMID 41203575, 2026). "Knockdown of SLC7A11 in tumor cells, overexpression of SLC7A11 in T cells, overexpression of GCLC in T cells, and cystine supplementation enhanced the anti-tumor ability of CD8+ T cells." (PMID 40018041, 2025). "The western blot results of protein extraction after tumor milling also indicated that the expression of GPX4, SLC7A11, and FADS2 proteins was decreased in the UA group." (PMID 40535804, 2025). "In ketogenic diet-fed tumor-bearing mouse models, we also observed a significant increase in lipid peroxidation and other related biomarkers, while CAV1 and SLC7A11 levels were markedly decreased compared to the normal diet group." (PMID 40180904, 2025). "Further, SLC7A11 is frequently overexpressed in various cancers, including HCC, and its upregulation can facilitate tumor growth." (PMID 39744233, 2025). "The tumor-suppressor activity of BAP1 is partly mediated by ferroptosis through deubiquitination of H2A on the SLC7A11 promoter, resulting in repression of SLC7A11 expression." (PMID 40109379, 2025). "SLC7A11 promotes glutathione (GSH) synthesis and reduces the generation of lipid hydroperoxides (L-OOH) to protect tumor cells from oxidative stress and ferroptosis." (PMID 39990661, 2025). "Brusatol, a quassinoid from Brucea javanica, induces ferroptosis in OSCC by inhibiting the Nrf2/GCLC pathway, leading to SLC7A11 suppression, GSH depletion, Fe2+/ROS accumulation, and Cal-27 tumor growth inhibition." (PMID 41227330, 2025). "The coexpression of SLC1A5, SLC7A11 and SLC7A5 proteins has yet to be determined in BC and is therefore important for understanding the potential transport of Gln in and out of tumour cells." (PMID 39843491, 2025). "Irradiation also induces adaptive responses involving SLC7A11 or GPX4, inhibiting radiation-induced ferroptosis and promoting tumor cell survival, leading to radioresistance." (PMID 39990661, 2025). "Accordingly, ferroptosis inducers targeting either SLC7A11 or GPX4, along with radiotherapy, can radiosensitize tumor cells by promoting ferroptosis." (PMID 40837737, 2025). "Meanwhile, xCT (SLC7A11) is frequently overexpressed in HCC tissues, contributing to tumour development and metastasis." (PMID 41154605, 2025). "In HCC cell lines and the subcutaneous xenograft model, the combined suppression of SLC7A11 and NQO1 significantly enhanced the inhibitory effect on tumor growth by inducing ferroptosis." (PMID 40007539, 2025). "In our study, Na-OHB induces ferroptosis in tumor cells by downregulating the genes regulated by CAV1/AMPK/NRF2 and affecting the interaction between CAV1 and SLC7A11." (PMID 40180904, 2025).